SEMA3B (semaphorin 3B)
Description:
Inhibits axonal extension by providing local signals to specify territories inaccessible for growing axons.
Synonyms: SEMA5; SEMAA; SemA; semaV; LUCA-1
Tractability: Antibody: UniProt places it where antibodies can reach, with medium confidence; UniProt predicts a signal peptide or a membrane-spanning region; its Gene Ontology location is reachable by antibodies, with medium confidence.
Gene: Protein-coding gene on chromosome 3 (50,267,542 to 50,277,546, forward strand). Ensembl gene ENSG00000012171.
Subcellular location: Secreted; Endoplasmic reticulum
Gene Ontology:
Molecular function: chemorepellent activity; neuropilin binding; semaphorin receptor binding
Biological process: axon guidance; cell-cell signaling; chemorepulsion of axon; negative chemotaxis; neural crest cell migration; positive regulation of cell migration; semaphorin-plexin signaling pathway
Cellular component: extracellular matrix; endoplasmic reticulum; plasma membrane; extracellular region
Genetic constraint (gnomAD): Loss-of-function variants: 69 observed, 69.14 expected, observed/expected ratio (o/e) 1, 90% interval 0.82 to 1.22. The upper end of that interval is the gene's LOEUF score, 1.22, which puts it in group 5 of 6, group 1 being the genes least tolerant of losing a copy. Missense variants: 957 observed, 924.44 expected, observed/expected ratio (o/e) 1.04, 90% interval 0.98 to 1.09. Synonymous variants: 465 observed, 402.17 expected, observed/expected ratio (o/e) 1.16, 90% interval 1.07 to 1.25.
Homologues: Orthologues: chimpanzee SEMA3B (99% identical), macaque SEMA3B (97% identical), dog SEMA3B (90% identical), pig SEMA3B (90% identical), rabbit SEMA3B (90% identical), rat Sema3b (89% identical), mouse Sema3b (89% identical), guinea pig SEMA3B (87% identical), tropical clawed frog sema3b (63% identical), zebrafish sema3b (63% identical). Paralogues in human: SEMA3A (54% identical), SEMA3G (47% identical), SEMA3F (46% identical), SEMA3D (46% identical), SEMA3E (45% identical), SEMA3C (43% identical), SEMA4C (31% identical), SEMA4B (30% identical), SEMA5B (30% identical), SEMA4D (30% identical), SEMA4G (30% identical), SEMA6A (28% identical), and 7 more.
Diseases named in the same sentence as SEMA3B in open-access papers:
SEMA3B is named in the same sentence as 60 diseases in open-access papers, as found by Europe PMC text mining. Sharing a sentence is not in itself a finding about the gene and the disease. The quoted sentences say what the papers report.
lung carcinoma (16 papers, 2004 to 2024). "SEMA3B is located in a site of frequent allele loss and hypermethylation in lung cancers, and experimental evidence indicated its role as tumor suppressor gene also in this context 8,80,81." (PMID 33537086, 2021). "In experimental preclinical models in mice, the forced expression of Sema3B impaired lung cancer growth, possibly accounted by anti-angiogenic activity." (PMID 33537086, 2021). "Sema3B inhibits the anchorage-independent growth of lung cancer cells inducing apoptosis by direct inhibition of the tumor cells." (PMID 30696103, 2019). "On the other hand, SEMA3B was previously demonstrated to inhibit proliferation of breast and lung cancer cell lines in vitro." (PMID 25961819, 2015). "Recently, SEMA3B was also demonstrated to be inactivated in lung cancer by promoter region hypermethylation." (PMID 15534609, 2004). "Indeed, sema3F and sema3B have been characterized as bona fide tumor suppressors of lung cancer, and sema3A has been found to function as an endogenous angiogenesis inhibitor that is down-regulated during tumor progression." (PMID 30696103, 2019). "Recent studies have revealed that SEMA3B could be a tumor suppressor in various cancer types, including lung cancer, breast cancer, and esophageal squamous cell carcinoma." (PMID 30863497, 2019). "Sema3B was initially characterized as a tumor suppressor of lung cancer and was found to inhibit the progression of additional forms of cancer such as breast cancer, endometrial cancer, osteosarcoma and oral cancer because of the direct effects on the tumor cells." (PMID 30696103, 2019). "Promoter hyper-methyletion of sema3B was associated with loss of heterozygosity (LOH) in both cell lines and primary tumors in lung cancer and hepatocellular carcinoma, and there is a statistically significant correlation between the sema3B methylation status and LOH at 3p21.3." (PMID 30696103, 2019). "Re-expression of SEMA3B inhibited lung cancer cell growth and induced apoptosis." (PMID 15534609, 2004). "Interestingly, substitution of a single nucleotide of sema3B that was found primarily in African-Americans and Latino-Americans but not in Caucasians, results in reduced lung cancer risk for an unknown reason." (PMID 30696103, 2019). "For example, semaphorin 3B (SEMA3B) and 3F (SEMA3F) were initially identified as tumor suppressors in lung cancer, because small cell lung cancer is correlated with a deletion in the short arm of chromosome 3 (3p21)." (PMID 30532711, 2018). "Although SEMA3F and SEMA3B are generally regarded as tumor suppressors and methylated SEMA3F has been reported in lung cancers, it is neo-expression instead of suppression of SEMA3/Plexin expression that is generally observed in PDACs." (PMID 23251334, 2012). "Semaphorin 3B (SEMA3B) can be used to be the tumor suppressor gene to suppress the Akt signal transduction pathway, which is achieved via the neuropilin-1 receptor in lung cancer cells." (PMID 33014809, 2020). "Some genes such as MMP11 (extra-cellular matrix proteins), XRCC1 (DNA repair), VEGF (regulator of angiogenesis), Cyclin D1 (cell cycle regulators) and tumor-suppressor genes (Semaphorin 3B, WNT-5A) have been found as down-regulated genes during lung cancer progression." (PMID 29593668, 2018).
breast carcinoma (15 papers, 2010 to 2024). "SEMA3B is associated with glioblastoma multiforme, uveal melanoma, breast cancer, gastric cancer, and other tumors." (PMID 39493752, 2024). "An elevated expression of the secreted semaphorin Sema3B in breast cancer samples has been associated with better prognosis." (PMID 33537086, 2021). "For instance, Sema3B induces apoptosis in lung and breast cancer but is associated with poor prognosis and survival of glioma patients." (PMID 23050142, 2012). "Lower mRNA expression of LRP1B and SEMA3B was detected in breast cancer than normal breast tissues, and their downregulation was in relation to poor clinical outcomes." (PMID 35186006, 2021). "All SEMA3s except SEMA3B (P = 0.35) were significantly differentially expressed in breast cancer tumours compared to adjacent normal (P < .00001), where only SAEMA3F has significantly increased expression." (PMID 32241267, 2020). "Sema3B, for instance induces apoptosis in lung and breast cancer, whereas Sema3F shows antiproliferative and antiangiogenic functions in melanoma, lung, breast, and colorectal cancers." (PMID 23050142, 2012). "For example, CST1 is highly expressed in Luminal B breast cancer cells, SEMA3B is highly expressed in HER2-positive breast cancer cells, while SEMA3B stands out in the analysis of progression-free survival, and PLAT is highly expressed in basal-like breast cancer cells." (PMID 39493752, 2024). "The genes for semaphorins 3B and 3F (SEMA3B and SEMA3F) are located at chromosome 3p21.3, which is a site of frequent allelic loss and acquired promoter methylation in breast cancer, resulting in the loss of gene expression, implicating them as tumour suppressors." (PMID 37685898, 2023). "SEMA3B, a secreted axonal guidance molecule, suppresses breast cancer development and metastasis." (PMID 35186006, 2021). "Genes extracted from the mRNA dataset, which show great significance in the development of breast cancer, are CENPA, MACF1, UGT2B7 and SEMA3B." (PMID 35205681, 2022). "Considering the fact that the biological function of SEMA3B has been proposed, we seek to unveil the function of NPPA in breast cancer." (PMID 34616853, 2021). "Furthermore, SEMA3B and its receptor, NRP-1, downregulate phosphatidylinositol-3-kinase (PI3K)/AKT signalling in breast cancer cells to restrict proliferation and inhibit tumour growth." (PMID 37685898, 2023). "By contrast, SEMA3B had similar higher expression in normal-like, LumA, and LumB than in Her2 and Basal like tumours, and SEMA3F had significantly higher expression in Her2, LumA, LumB than in normal and basal type of breast cancer." (PMID 32241267, 2020).
glioma (7 papers, 2008 to 2022). A benign or malignant brain and spinal cord tumor that arises from glial cells (astrocytes, oligodendrocytes, ependymal cells). "The loss of chromosome 3p21, which harbors several tumor-suppressor genes, such as BLU, RASSF1A, and SEMA3B, are frequently observed in cancers including gliomas, and the 3p21.31 region is a female-specific risk locus in astrocytoma and GBM." (PMID 33981597, 2021). "An increase in expression of the Sema3B gene was found to be associated with poor prognosis and survival of glioma patients." (PMID 23050142, 2012). "On the contrary, it was shown that low SEMA3B expression associated with poorer OS in gliomas, but when associated with expression of two other genes, osteonectin/SPARC and doublecortex/doublecortin." (PMID 18781179, 2008). "Suppression of microRNA-221 in glioma cells inhibited cell proliferation and invasion via decreasing SEMA3B." (PMID 35656090, 2022). "Mechanistic experiments validated that miR-221 participates in regulating glioma cells proliferation and invasion via suppression of a direct target gene, the Semaphorin 3B (SEMA3B)." (PMID 26197878, 2015). "Mechanistically, SEMA3B is the direct target of miR-221, which acts as the tumor suppressor in glioma." (PMID 26197878, 2015). "Further researches to assess the effects of miR-221 on glioma cells proliferation and invasion were carried on, as well as the regulating mechanism on SEMA3B gene was explored." (PMID 26197878, 2015). "Yet a later study reported the opposite by demonstrating positive correlations of Sema3B, Sema3G and neuropilin-2 with prolonged survival in glioma patients." (PMID 23050142, 2012). "In our study, the expression level of SEMA3B in glioma cells was found lower than normal glia cells, which is the first observation of SEMA3B in glioma cells to our knowledge and further result suggest that SEMA3B participates in the regulation of glioma cells proliferation and invasion." (PMID 26197878, 2015). "Taken together, our findings highlight an unappreciated role for miR-221 and SEMA3B in glioma." (PMID 26197878, 2015). "We manipulated the expression of miR-221 using mimic or inhibitor both in the Normal Human Astrocytes (NHA) and human glioma U87MG cells, and the SEMA3B level was detected using western blot." (PMID 26197878, 2015). "In conclusion, SEMA3B, SEMA3G and NRP2 expressions were related to prolonged survival of adult patients with glial tumours." (PMID 18781179, 2008). "Statistical analysis indicated that SEMA3B, SEMA3G and NRP2 expressions were related to prolonged survival and that SEMA3D expression was reduced in high-grade as compared with low-grade gliomas." (PMID 18781179, 2008). "Among the tested semaphorins, SEMA3B and SEMA3G mRNA levels proved to be a prognostic marker for OS in our cohort including 11 low-grade and 27 high-grade gliomas (P=0.029 and P=0.016, respectively)." (PMID 18781179, 2008). "Moreover, in the study by Karyian-Tapon and co-authors, higher mRNA expression of SEMA3B, SEMA3G and NRP2 were related to prolonged survival of patients with the diagnosis of glial tumors." (PMID 33036421, 2020). "We firstly analyzed the correlation of the expression of miR-221 and SEMA3B level in 30 human glioma samples using RT-qPCR, and out result presented that there was a negative correlation between miR-221 and SEMA3B." (PMID 26197878, 2015). "As VEGF165 binds to NRP2, competition between SEMA3B/3G and VEGF165 for binding to NRP2 might exist in gliomas as demonstrated for SEMA3A and NRP1 in ECs." (PMID 18781179, 2008).
gastric cancer (6 papers, 2015 to 2025). A primary or metastatic malignant neoplasm involving the stomach. "SEMA3B (Semaphorin 3B), a tumor-suppressing axon guidance factor, has been shown to induce apoptosis in a range of cancers, including the lung, renal, and gastric cancer." (PMID 35656090, 2022). "Down-regulation of SEMA3B gene was negatively correlated with tumor size and gastric cancer staging." (PMID 25961819, 2015). "Downregulation of miR-6872-5p has been detected in GCA tissues and gastric cancer cells, and it may act as tumor-suppressor miRNA synergistic with its host gene SEMA3B, inhibiting GCA cell migration and invasion." (PMID 33537086, 2021).
ovarian carcinoma (5 papers, 2011 to 2023). A malignant neoplasm originating from the surface ovarian epithelium. "Indeed, deletions occur in the region 3p21.3 of the short arm of chromosome 3, a region encoding for Sema3B and Sema3F in various cancers, including lung cancer and even ovarian cancer." (PMID 24212788, 2011). "Sema3b inhibited axonal extension and exerted an antitumor effect on lung and ovarian cancer cells in vitro." (PMID 37056757, 2023). "In lung and ovarian cancer cells, Semaphorin 3B (Sema3B) expression decreases colony formation, proliferation, and even tumorigenicity in murine xenograft experiments." (PMID 24212788, 2011). "Interestingly, a significantly reduced expression of Sema3B (83 kDa), Sema3F (90 kDa), and plexin-A3 was observed in human ovarian cancer cell lines when compared with normal human ovarian surface epithelial cells." (PMID 24065959, 2013).
melanoma (4 papers, 2021 to 2024). A malignant, usually aggressive tumor composed of atypical, neoplastic melanocytes. "In particular, comparative hybridization of cDNA arrays between highly and weakly invasive melanoma cells, and further confirmation by quantitative RT-PCR, identified Sema3B downregulation in highly invasive cells." (PMID 33858502, 2021). "The only evidence about Sema3B role in melanoma was published in 2001." (PMID 33858502, 2021). "However, the biological mechanism behind SEMA3B expression and the prognosis and initiation of malignant melanoma is not clear yet." (PMID 36793711, 2023).
Arthritis (3 papers, 2022 to 2026). Inflammation of a joint. "More importantly, Sema3B deficiency enhances the severity of serum-induced arthritis, while Sema3B administration abrogates this effect." (PMID 38283352, 2023). "Previous works from our group show that Semaphorin3B (Sema3B) is reduced in RA and plays a protective role in a mouse arthritis model." (PMID 38283352, 2023). "In fact, ERK is overactivated in the joints of Sema3B-/- arthritic mice and synovial tissue from patients with RA and from patients with early arthritis who develop erosive RA." (PMID 36231105, 2022). "For instance, SEMA3B protects against tissue damage in arthritis." (PMID 41716378, 2026). "Furthermore, genetic knockdown of Sema3B induces higher arthritis severity together with higher expression of cytokines, chemokines, and matrix metalloproteinase." (PMID 36231105, 2022).
glioblastoma (3 papers, 2015 to 2024). The most malignant astrocytic tumor (WHO grade IV). "For example SEMA3D and SEMA3E displayed strong inhibitory effect on the glioblastoma cells whereas SEMA3A and SEMA3B expression just caused persistent cell shape contraction." (PMID 25961819, 2015).
small cell lung carcinoma (3 papers, 2012 to 2018). Small cell lung cancer (SCLC) is a highly aggressive malignant neoplasm, accounting for 10-15% of lung cancer cases, characterized byrapid growth, and early metastasis. "The small-cell lung carcinoma cell line U2020 was transfected with pETE/SEMA3B or pETE as the control." (PMID 25961819, 2015). "The implication of semaphorins in cancer development was first suggested by the observation of a deletion of chromosomal region 3p21, where Sema3B and Sema3F reside, in almost all cases of small cell lung cancer (SCLC)." (PMID 23050142, 2012). "With the use of the small cell lung cancer cell line U2020 we confirmed the function of SEMA3B as a tumor suppressor, and showed that the suppression can be realized through the induction of apoptosis and, possibly, associated with the inhibition of angiogenesis." (PMID 25961819, 2015).
membranous nephropathy (2 papers, 2021 to 2024). "Other novel proteins including neural epidermal growth factor-like 1 protein (NELL-1) and Semaphorin 3B have recently been identified to be associated with membranous nephropathy." (PMID 33413188, 2021).
osteoporosis (2 papers, 2021 to 2025). A condition of reduced bone mass, with decreased cortical thickness and a decrease in the number and size of the trabeculae of cancellous bone (but normal chemical composition), resulting in increased fracture incidence. "Moreover, Sema3B was found to be involved in estrogen deficiency-induced osteoporosis." (PMID 33727932, 2021). "It inhibits miR-21 and semaphorin 3B (Sema3B) via Wnt/β-catenin signaling, impairing MSC osteogenic differentiation in estrogen-deficient osteoporosis, leading to reduced bone mineral density and trabecular abnormalities." (PMID 40873591, 2025).
preeclampsia (2 papers, 2016 to 2024). Preeclampsia is a hypertensive disorder of pregnancy that is characterized by new-onset hypertension with proteinuria presenting after 20 weeks of gestation, and depending on mild or severe forms may initially present with severe headache, visual disturbances, and hyperreflexia. "Based on this finding, the authors proposed that factors in the maternal milieu cause reversible upregulation of SEMA3B in trophoblasts in preeclampsia." (PMID 27590522, 2016). "This study also observed an upregulation of the angiogenesis inhibitor SEMA3B in trophoblasts obtained from women with preeclampsia." (PMID 27590522, 2016). "In this regard, high SEMA3C levels have been found at the maternal–fetal–placental interface during the first trimester of gestation, and SEMA3F, SEMA3B, and NRP2 are overexpressed in the placenta of women with preeclampsia." (PMID 38541683, 2024).
prostate carcinoma (2 papers, 2019). A carcinoma that arises from epithelial cells of the prostate gland. "Single nucleotide polymorphisms in the genes encoding sema3B and sema3F were also associated with prostate cancer risk and poor prognosis of prostate cancer." (PMID 30696103, 2019). "High levels of SEMA3B expression are associated with better survival of prostate cancer patients." (PMID 30863497, 2019). "Our results showed that the expression levels of SEMA3B and BTG2 in the TSPX-high prostate cancer samples were similar with those in the non-tumor prostate samples (P-value > 0.05), while those in TSPX-low prostate cancer samples were significantly low." (PMID 30863497, 2019).
renal carcinoma (2 papers, 2015 to 2017). A carcinoma arising from the epithelium of the renal parenchyma or the renal pelvis. "Thus, the methylation of both CpG-islands of the SEMA3B gene is a hallmark of lung and renal cancer." (PMID 25961819, 2015). "We conclude that aberrant expression and methylation of SEMA3B could be suggested as markers of lung and renal cancer progression." (PMID 25961819, 2015). "Furthermore we aimed to evaluate frequencies of promoter (hg38/chr3: 50,267,308–50,267,797) and intronic (hg38/chr3: 50,268,972–50,269,271) CpG-island hypermethylation correlations with SEMA3B expression, and tumor progression in lung and renal cancers." (PMID 25961819, 2015).